Y_RNA (Y RNA )
Gene: Miscellaneous RNA gene on chromosome X (68,361,075 to 68,361,187, forward strand). Ensembl gene ENSG00000206646.
Homologues: Orthologues: chimpanzee Y_RNA (100% identical), macaque Y_RNA (97% identical). Paralogues in human: RNY1 (91% identical), Y_RNA (90% identical), Y_RNA (89% identical), Y_RNA (88% identical), RNY1P11 (87% identical), RNY1P7 (87% identical), Y_RNA (87% identical), Y_RNA (86% identical), Y_RNA (85% identical), RNY1P8 (84% identical), Y_RNA (84% identical), RNY1P15 (83% identical), and 97 more.